CX3CL1 (C-X3-C motif chemokine ligand 1)
Diseases named in the same sentence as CX3CL1 in open-access papers (continued):
Sharing a sentence is not in itself a finding about the gene and the disease.
cancer (continued). "Therefore, higher concentration of CX3CL1 in bone marrow and serum are required to recruit cancer cells with low CX3CR1 expression." (PMID 28122354, 2017). "CX3CL1 can be expressed by cancer cells and endothelial cells." (PMID 28399860, 2017). "Moreover, Erreni and colleagues demonstrated that glioblastoma cancer stem cells and progenitor cells express both CX3CL1 and CX3CR1, indicating that this axis operates early in tumorigenesis process." (PMID 24799766, 2014). "The role of the CX3CL1/CX3CR1 axis in cancer pathogenesis has long been discussed." (PMID 24799766, 2014). "Notably, the increased CX3CL1 secretion induced by all the tested actives of 2LC1, if further confirmed, may offer clinical benefits in the context of cancer." (PMID 40362536, 2025). "The role of CX3CL1 may vary significantly between different types of cancer." (PMID 41210693, 2025). "Interestingly, the prognostic role of CX3CL1 varies across different cancers." (PMID 40051011, 2025). "Therefore, the difference in CX3CL1 expression might not represent the severity of the disease since it is challenging to determine which subclones of cancer gain CX3CL1 expression." (PMID 38775151, 2024). "Moreover, overexpression of CX3CL1 partially reversed the pro-cancer effect of LPS on OSCC." (PMID 38915444, 2024). "Consequently, the relationship between CX3CL1 expression and cancer immunity was investigated." (PMID 37153002, 2023). "Therefore, cancer cells expressing CX3CL1 in response to therapy may promote immune cell infiltration into the TME, thereby improving overall survival." (PMID 36869384, 2023). "High CX3CL1 expression was associated with favorable prognosis in CESC and KICH, suggesting that CX3CL1 may be a potential biomarker for prediction the prognosis of these two cancer types." (PMID 37153002, 2023). "CX3CL1 is a chemokine that may play important roles in cancer immune regulation." (PMID 34671562, 2021). "However, the CX3CL1:CX3CR1 axis presents either pro- or antitumor effects in different cancers." (PMID 35140706, 2021). "In addition, some cancers enhance the pro-cancer properties of CX3CL1." (PMID 32466280, 2020). "Hence, the CX3CL1-macrophage axis may exert an important function in the transformation from inflammation to cancer." (PMID 33426088, 2020). "However, there is much debate concerning the relevance of CX3CL1 to cancer growth and progression." (PMID 28122354, 2017). "Increased expression of CX3CL1 recruits the CX3CR1‐positive macrophages to liver PMN, resulting in the upregulation of MMP9, which facilitated the migration of immune cells and cancer cells." (PMID 40032646, 2025). "The interaction between osteoblasts, bone marrow stromal cells, and cancer cells is largely driven by chemokine signaling, particularly the CXCL12/CXCR4 and CX3CL1/CX3CR1 axes." (PMID 40606222, 2025). "The heatmap displayed that GPX4 expression was highly correlated with the levels of numerous chemokines and chemokine receptors, such as CXCL16, CCL28, CX3CL1, CCL5, CCR10, CXCR5, and CXCR3, across the majority of cancer types." (PMID 41142608, 2025). "Gene groups linked to efferocytosis, including Tyro3, Axl, MerTK, Gas6, BAI-1, CX3CL1, CD31, CD47, Rac1, and the TIM family, represent significant targets for prospective cancer therapies." (PMID 39911848, 2025). "There are a few chemokines that are positively correlated with ASPP1 in cancers, such as CCL28, CX3CL1, CXCL14, and CXCL17." (PMID 39830645, 2024). "We selected eight candidates (CST4, CCL20, CX3CL1, CXCL5, CXCL8, GDF15, CCL5 and MMP3) that play an important role in cancer pathogenesis for further study." (PMID 38385965, 2024). "Extracting, organizing, and analyzing the TCGA database on the expression of CX3CL1 and its receptor CX3CR1 in cancer tissues and corresponding paracancerous normal tissues of OSCC patients by bioinformatics methods." (PMID 38915444, 2024).
cancer (continued). "This study revealed that CX3CL1 has an anti-cancer effect in OSCC and that the pro-cancer effect of LPS on CX3CL1 overexpression has a partial reversal effect." (PMID 38915444, 2024). "Fractalkine/CX3C chemokine ligand 1 (CX3CL1) and its receptor CX3CR1 have been found to allow immature dendritic cells to migrate to cancer cells using the expression of their receptor CX3CL1." (PMID 38886862, 2024). "This phenomenon has been demonstrated by CX3CL1 overexpression in indolent and aggressive murine cancer models, where MOC1 and MOC2 cancer subclones had different responses to CX3CL1 overexpression." (PMID 38775151, 2024). "Cells pre‐treating c‐Jun siRNA abolishes CX3CL1‐induced cell migration and ICAM‐1 expression, demonstrating that c‐Jun phosphorylation mediates CX3CL1‐induced cancer metastasis and ICAM‐1 expression." (PMID 37082943, 2023). "Studies also demonstrated that CX3CL1 and its unique chemokine receptor CX3CR1 played an essential role in cancer development." (PMID 37082943, 2023). "This suggests that genes in our signature have an impact on the physiological processes of cancer cells, especially the CXCL2 and CX3CL1 genes." (PMID 37021054, 2023). "What’s more, The GEPIA2 database uncovered eight novel cancer types (BRCA, DLBC, GBM, LUAD, PAAD, READ, STAD, and THYM) with high CX3CL1 expression, although BRCA had lower CX3CL1 expression previously." (PMID 37153002, 2023). "Cell-cell interaction analysis showed that the CX3CL1-CX3CR1 pair was significantly enriched between Mono_CX3CR1 cells and cancer cells from MPR patients, indicating that CX3CL1 expression in cancer cells attract Mono_CX3CR1 monocytes in MPR patients." (PMID 36869384, 2023). "Given the expression of CX3CL1 in cancer cells from MPR patients, it was possible that NK_FCGR3A cells were recruited into the TME by CX3CL1." (PMID 36869384, 2023). "Due to the scarcity or low number of normal tissues of specific cancer types in the TIMER2 database, the basic expression level of CX3CL1 was also evaluated using the GTEx data from the GEPIA2 database." (PMID 37153002, 2023). "CX3CL1 expression was positively correlated with the infiltration levels of CD4+ T cells, M1 macrophage cells, and activated mast cells in various cancers." (PMID 37153002, 2023). "Proverbially, the CX3CL1/CX3CR1 axis is significantly related to anti-inflammatory, anti-fibrosis, anti-rejection, and anti-cancer activities in the treatment of renal diseases." (PMID 36969169, 2023). "This indicated a clear role of miR-200-3p in increasing CX3CL1 and CX3CR1 expression in cancer cells." (PMID 37770496, 2023). "In the OFB, Tbet (involved in NK cell maturation and function) is increased and Cx3cl1, Ifng and Mscf2 are decreased by the HFD with little response to the cancer cells while increased in the PSF in both cancer groups." (PMID 38264656, 2023). "The combination of HFD plus cancer resulted in increased expression of some cytokines in the OFB (e.g., Ccl2, Ccl4, Cxcr2, Il1b) and decreased expression of others (e.g., Ccr5, Cx3cl1, eNos, Tnfa) as compared to the HFD group alone." (PMID 38264656, 2023). "However, CX3CL1 may also produce a cancer-promotive effect as an adhesion molecule." (PMID 34671562, 2021). "There is vast evidence that fractalkine/CX3CL1 is actively involved in many states related to inflammation such as atherosclerosis, HIV infection, or cancer." (PMID 34698104, 2021). "To evaluate whether CX3CL1 expression is associated with disease aggressiveness with functional experiments, we evaluated the expression levels in 3 different types of cell lines, TCCSUP (grade IV cancer), 5637 (grade II cancer), and T24 cells (high-grade and invasive TCC)." (PMID 34671562, 2021). "Our previous study showed that the vertebral marrow sinusoids were full of CX3CL1, which plays an important role in the process of spine metastases derived from CX3CR1-expressing cancer cells." (PMID 32390803, 2020).
cancer (continued). "CCL2, CXCL10, and CX3CL1/CX3CR1 can serve as both favorable and unfavorable prognostic factors for cancers depending on cancer types." (PMID 31991604, 2020). "The mechanisms, by which the CX3CL1/CX3CR1 axis affects the pathogenesis and survival of cancer cells, are poorly explored." (PMID 29867042, 2018). "Concordantly, the simultaneous targeting of mouse Vegfr2 and DLD1 carcinoma-produced VEGF-A with the antibodies DC101 and bevacizumab, respectively, led to increased vascular expression of Cx3cl1 and reduced extravasation of HPMo to DLD1 xenografts." (PMID 29367702, 2018). "Particularly, many cancer-related genes including CDH5, BVES, CX3CL1, FGFR1, IGF1 and CD40 were identified in SIN_D." (PMID 25774687, 2015). "This review will summarize the multiple roles of the CX3CL1/CX3CR1 axis in the pathogenesis of inflammation and cancer." (PMID 24799766, 2014). "A 90-kDa protein, corresponding to the expected size of the full-length CX3CL1, was detected in EOC biopsy samples, in CD326+ epithelial cells from malignant ascites and in SKOV3, BG1 and OVCAR3 cells." (PMID 21750716, 2011). "Moreover, compared with other cancers, FAT1 expression in BRCA showed the strongest positive enrichment with CX3CL1 and numerous CXCL cytokines." (PMID 40083689, 2025). "Also, inflammation is involved in cancer proliferation and multiple pro-inflammatory cytokines (e.g., CCL5, CX3CL1, and CXCL12) play a role in cancer." (PMID 40943574, 2025). "Similarly, in human metastasis cancer cell lines, metastatic cell line HSC-3-M3, derived from HSC-3, showed increased CX3CL1 expression compared with HSC-3 cells." (PMID 38775151, 2024). "Furthermore, we discovered that CX3CL1 affected the biological characteristics of OSCC by influencing the EMT process and AKT activation, and partially reversed the pro-cancer effect of LPS-induced inflammation on OSCC." (PMID 38915444, 2024). "Increased levels of CX3CL1 (from 75 to 115 pg/mL, p = 0.0056) and CCL11 (from 13 to 20 pg/mL, p = 0.0077) were also observed in S + M2, which can be explained by the interaction of 4T1/GFP cancer cells with the M2 activation factor IL-4." (PMID 37445941, 2023). "In the remaining cancer types, there was no discernible difference in CX3CL1 expression between normal and malignant tissues, regardless of the inclusion or exclusion of the GTEx dataset." (PMID 37153002, 2023). "Other types of cancer tissues and comparable normal tissues showed no discernible differences in CX3CL1 methylation." (PMID 37153002, 2023). "Relevantly, clinical samples exhibited a negative correlation between miR-561-5p expression and levels of CX3CL1 and CX3CR1+ in NK cells, cells that exhibit a relevant antitumor response 38, suggesting that CX3CL1 could have clinical relevance in cancer." (PMID 33391453, 2021). "In the cancer microenvironment DPMSCs secrete pro-adhesive molecules, including BMP2, CX3CL1, and VEGFA, which may regulate the adhesive properties of MDA231 cells through their paracrine effect or through their secretome; this needs to be examined." (PMID 34944000, 2021). "In the absence of CX3CL1, this has a negative effect because if cancer cells get into the bloodstream a site-specific metastasis occurs, as described later in the article." (PMID 32466280, 2020). "We propose that CX3CL1, E-cadherin, N-cadherin, and FOXA2 show a lot of potential as downstream target genes of hsa-miR-590-3p signifying hsa-miR-590-3p's indirect effect on EMT and in turn cancer progression." (PMID 31781476, 2019). "However, CX3CL1 function in HCC and in NK cells-mediated eradication of cancer cells remains largely uncharacterized." (PMID 31367257, 2019). "While no direct impact of CX3CL1 expression on cancer cell apoptosis was identified in co-culture assays it became apparent that CX3CL1 is acting in a paracrine fashion, leading to an increased recruitment of inflammatory cells." (PMID 29867042, 2018).
cancer (continued). "Alternatively, other chemotactic stimuli rather than elevated CX3CL1 in bone marrow and serum recruit such cancer cells." (PMID 28122354, 2017). "The CX3CL1/CX3CR1 axis plays an important function in the pathophysiology of several inflammatory, infectious, and neurological processes and in various forms of cancers." (PMID 24799766, 2014). "Therefore, our study found that the anti-cancer effect of CX3CL1 on OSCC does not conflict with the increased production of CX3CL1 in LPS-stimulated OSCC." (PMID 38915444, 2024). "Correlation analysis between RFC4 and checkpoint gene expression in different types of cancers showed a high correlation with immune genes including CCL4, CCL16, HLA family genes, TNFRSF8, TNFRSF14, TNFRSF18, CD70, CD44 (p < 0.05), CD276, CX3CL1 and VGEGFA (p < 0.05)." (PMID 39031628, 2024). "CX3CL1 is released by immunogenic apoptotic cancer cells regardless of the cancer cell type." (PMID 39011040, 2024). "Considering these findings, CX3CL1 can increase the formation of lymphatic structures, change LV integrity, and simultaneously promote CX3CR1+ recruitment through LVs, thus resulting in increased metastasis of cancer cells to cervical LNs via the lymphatic pathway." (PMID 38775151, 2024). "However, there has been no comprehensive study on the correlation between CX3CL1 and cancers on the basis of clinical features." (PMID 37153002, 2023). "Other cancer patients showed no discernible relationship between age and CX3CL1 expression." (PMID 37153002, 2023). "Like CXCL6, CX3CL1 can be cleaved and released by disintegrin or metalloproteinases but also by cathepsin S. Depending on the context, the expression of CX3CR1 and/or CX3CL1, in a wide number of cell types, may lead to opposite effects on cancer progression." (PMID 36429101, 2022). "C-X3-C motif chemokine ligand 1 (CX3CL1)/fractalkine is a chemokine released after cleavage by two metalloproteases, ADAM metallopeptidase domain 10 (ADAM10) and ADAM metallopeptidase domain 17 (ADAM17), involved in inflammation and angiogenesis in the cancer microenvironment." (PMID 30845779, 2019). "In addition, it has been demonstrated that CX3CL1/CX3CR1 signaling activity in spinal microglia is an essential process for development and maintenance of inflammatory pain, neuropathic pain and cancer pain." (PMID 25768734, 2015). "However, CX3CL1 does not influence indolent cancer metastasis." (PMID 38775151, 2024). "However, the role of CX3CL1 in OSCC is not well understood and has been subject to controversy.CX3CL1 exhibits markedly different effects in different types of tumors, especially in OSCC, where research is limited and whether it promotes or inhibits cancer remains unclear." (PMID 38915444, 2024). "Some cancer cells have high levels of transmembrane ligands called CXCL16 and CX3CL1 but do not produce the corresponding receptors for these molecules." (PMID 26796342, 2016). "However, CX3CL1 did not influence the metastatic ability of the indolent, nonmetastatic MOC1 cancer cells (data not shown)." (PMID 38775151, 2024).
infection (42 papers, 2010 to 2026). The state of being infected such as from the introduction of a foreign agent such as serum, vaccine, antigenic substance or organism. "In this study, we found elevated levels of CX3CL1 in patients with S. aureus infections—especially in infections involving the respiratory tract." (PMID 41081526, 2025). "CX3CL1 expression was found to be preserved and highly expressed in the cardiac tissue of both treated and untreated mice 10 days post-infection." (PMID 40936920, 2025). "The interaction between CX3CL1 and CX3CR1 plays a crucial role in the immune response to RSV infection because mice genetically deficient in CX3CR1 develop more severe cases of infection." (PMID 39337288, 2024). "Only infection with RSV and treatment with LPS induced CX3CL1 expression in A549 cells, and treatment with both variants of RSV sG, BSA or LTA did not." (PMID 40295855, 2024). "CX3CL1 is a transmembrane protein on the surface of epithelial cells and contributes to the cell adhesion of leukocytes during infection." (PMID 37896776, 2023). "In vitro infection of HUVECs with R. africae showed a synergistic contribution of HUVECs and platelets to the elevation of sCD40L in a CX3CL1-dependent manner, potentially contributing to vascular inflammation and dysregulated hemostasis." (PMID 35993770, 2022). "The expression levels of CCL3, CCL5, CXCL10 and CX3CL1 in the brain tissue of infected mice was elevated with the extension of infection time." (PMID 34017692, 2021). "CX3CL1 mRNA expression was also detected in the ipsilateral DRG of infected mice at the 30th day post-infection, and the i.t. injection of TNF-α or IL-1β in naïve animals induced CX3CL1 mRNA expression in the spinal cord and ipsilateral DRG." (PMID 31138231, 2019). "Since these cells exclusively express CX3CR1 in the healthy CNS, and its ligand CX3CL1 is constitutively expressed by neurons, this receptor:ligand interaction is likely to function during infection." (PMID 25324719, 2014). "We measured CX3CL1 mRNA levels in cells following infection in the presence of HDAC inhibitors, TSA (for HDAC1/2) and EX527 (for HDAC3 type Sirt1)." (PMID 23724129, 2013). "When H69 cells were exposed to C. parvum for infection for up to 24 h, a time-dependent increase in CX3CL1 both at the protein and message levels was detected." (PMID 23724129, 2013). "Furthermore, soluble G protein (sG) can bind to CX3CR1 and competitively interfere with cell signaling induced by the chemokine CX3CL1, resulting in inhibition of immune cell recruitment to the site of infection." (PMID 42043252, 2026). "In addition, in an in vivo murine model of S. aureus pneumonia, we observed reduced CX3CL1 levels in the BAL fluid of mice treated with GI254023X prior to infection." (PMID 41081526, 2025). "Infection of AECs with RSV increases the expression of several cytokines including CX3CL1." (PMID 39337288, 2024). "RABV-ERA strain infection in mouse brain at day 7 showed many differentially expressed upregulated miRNAs involved in immune-related pathway including mmu-miR-183 that potentially regulates CX3CL1." (PMID 37692167, 2023). "Further analysis of HIV infection showed the involvement of CX3CL1 in infection events." (PMID 37580951, 2023). "Furthermore, GAD DISEASE analysis demonstrated the involvement of CX3CL1 in “immune”, “infection”, and “cardiovascular” diseases." (PMID 37580951, 2023). "The expression of chemokine CX3CL1 increased with the prolongation of the infection time." (PMID 36169259, 2022). "While the exact mechanisms remain unknown, in vivo C3H/HeN mouse infection studies performed with R. conorii confirmed that the peak expression of CX3CL1 coincides with the recruitment of macrophages during the acute phase of systemic endothelial infection." (PMID 35993770, 2022).